CRP (C-reactive protein)
Diseases named in the same sentence as CRP in open-access papers (continued):
Sharing a sentence is not in itself a finding about the gene and the disease.
pneumococcal infection (35 papers, 2011 to 2026). Infections with bacteria of the species streptococcus pneumoniae. "While polymorphism in the CRP-encoding gene seems to occur rarely, some studies have shown association between polymorphism and susceptibility to pneumococcal infection in humans." (PMID 36622851, 2023). "CRP-deficient mice are more susceptible to pneumococcal infection than are wild type mice, which indicates that the trace level of endogenous mouse CRP is capable of exerting anti-pneumococcal functions." (PMID 30863393, 2019). "The three main proteins that have been investigated and associated with pneumococcal infection include C-reactive protein (CRP), serum amyloid P (SAP), and mannose-binding lectin (MBL)." (PMID 29988379, 2018). "Our findings are consistent with the significant association between clinical pneumococcal infection and non-coding human CRP gene polymorphisms which reduce CRP expression." (PMID 30459761, 2018). "Our findings are consistent with the significant association between clinical pneumococcal infection and non-coding human CRP gene polymorphisms which affect CRP expression." (PMID 24673624, 2014). "Here we show for the first time that CRP-deficient mice are remarkably susceptible to Streptococcus pneumoniae infection and are protected by reconstitution with isolated pure human CRP, or by anti-pneumococcal antibodies." (PMID 24673624, 2014). "Altogether, this study highlights the similarity of the host response to pneumococcus in zebrafish and humans, gives evidence of the conserved role of C-reactive protein in the defense against pneumococcus, and suggests novel host genes associated with pneumococcal infection." (PMID 36622851, 2023). "Finally, utilizing both forward and reverse genetics, we show that zebrafish that have defects either in the production or the structure of C-reactive protein (Crp) are more susceptible to a severe pneumococcal infection than wild type zebrafish." (PMID 36622851, 2023). "Vice versa, CRP-deficient mice had a worse outcome following Streptococcus pneumoniae infection and could be protected either by reconstitution with isolated pure human CRP, or by anti-pneumococcal antibodies." (PMID 35402541, 2022). "Experiments employing human CRP transgenic mice, CRP-deficient mice, and normal mice in which human wild-type CRP (WT CRP) was passively administered have all revealed that CRP is protective against pneumococcal infection." (PMID 33552084, 2020). "However, the CRP-deficient mice were remarkably susceptible to Streptococcus pneumoniae infection and were protected by reconstitution with isolated pure human CRP, or by anti-pneumococcal antibodies." (PMID 30459761, 2018). "C-reactive protein (CRP) was discovered as a protein that reacts with C-polysaccharides to form precipitates in the serum of patients with pneumococcal infection." (PMID 42274591, 2026). "We conclude that the protection against prolonged pneumococcal infection involves conformational changes in CRP, binding of CRP to both PCh and amyloids on the pneumococcal surface, and complement activation by PCh-complexed CRP." (PMID 40740789, 2025). "We conclude that the protection against prolonged pneumococcal infection requires structural changes in CRP and binding to both phosphocholine and amyloids on pneumococci." (PMID 40740789, 2025). "The ELISA results revealed that serum CRP remained stable in the course of pneumococcal infection (Fig. EV2B)." (PMID 41214213, 2025). "WT CRP protects mice against pneumococcal infection if administered to mice prior to inoculation with bacteria and does not protect if administered a few hours after inoculation." (PMID 40740789, 2025). "C-reactive protein (CRP) protects mice during the initial stages of Streptococcus pneumoniae infection." (PMID 40740789, 2025). "The significance of CRP in host defense against invasive pneumococcal infection was evaluated by two approaches." (PMID 41214213, 2025).
pneumococcal infection (continued). "It remains to be established that the ability of structurally altered pentameric CRP to bind to amyloids contributes to protection against pneumococcal infection." (PMID 40740789, 2025). "The combined data reported here and published previously suggest that SAP cooperates with CRP in protection against pneumococcal infection." (PMID 40740789, 2025). "Future investigations employing double SAP KO and CRP KO mice would provide definitive proof for the cooperation between SAP and CRP in controlling pneumococcal infection." (PMID 40740789, 2025). "Interest in this CRP was the result of a seminal discovery of its pattern of response to pneumococcal infection in humans." (PMID 37860004, 2023). "CRP is an acute phase reaction protein originally found in the study of pneumococcal infection, which is used to identify inflammation and severe infection, and guide the treatment of adults and children with antibiotics." (PMID 37442959, 2023). "Subsequently, the phosphocholine (PCh)-binding pocket on CRP turned out to be decisive for the beneficial CRP effect during early pneumococcal infection of mice." (PMID 35402541, 2022). "This assumption was once more modified by the later statement that mice were protected against pneumococcal infection by both PCh-dependent and PCh-independent CRP effects." (PMID 35402541, 2022). "Experiments in mice have revealed that one of the functions of CRP is to protect against pneumococcal infection by binding to pneumococci and activating the complement system." (PMID 33117400, 2020). "In this study, two CRP mutants, E-CRP-1 and E-CRP-2, were employed to investigate the mechanisms of anti-pneumococcal function of CRP in a mouse model of pneumococcal infection." (PMID 33117400, 2020). "We can conclude now that complement activation by phosphocholine-complexed CRP is indeed essential for CRP-mediated protection of mice against pneumococcal infection." (PMID 32903624, 2020). "The inability of H38R CRP to protect mice against pneumococcal infection was solely due to its inability to activate the complement system since the H38R mutation did not reduce the stability of CRP; H38R CRP was more stable than WT CRP in vivo." (PMID 32903624, 2020). "CRP binds to the phosphocholine determinant of the cell wall C-polysaccharide from S. pneumoniae and provides innate defense against pneumococcal infection." (PMID 30685351, 2020). "In murine models of pneumococcal infection, human CRP has been shown to be protective against lethality; however, the molecular mechanism of anti-pneumococcal action of CRP remains undefined." (PMID 33117400, 2020). "Based on the model for E-CRP-1 and E-CRP-2, we propose a possible mechanism of action of endogenous CRP in humans in pneumococcal infection." (PMID 33117400, 2020). "Despite several unanswered questions regarding the mechanisms of complement activation by human CRP in human and murine sera, we conclude that CRP cannot protect against pneumococcal infection if CRP is unable to activate the complement system." (PMID 32903624, 2020). "Employing a mouse model of pneumococcal infection, it has been shown that passively administered human wild-type CRP protects mice against infection, provided that CRP is injected into mice within two hours of administering pneumococci." (PMID 33552084, 2020). "CRP is also a component of the acute phase response and a critical host defense molecule of the innate immune system against pneumococcal infection." (PMID 33117400, 2020). "Previously, we investigated the role of the PCh-binding site of CRP in protection of mice against pneumococcal infection employing a CRP triple mutant, F66A/T76Y/E81A, incapable of binding to PCh and pneumococci." (PMID 32903624, 2020). "Overall, these findings indicate that a conformationally altered form of CRP capable of binding to factor H is necessary for protection against late-stage pneumococcal infection." (PMID 33117400, 2020).
pneumococcal infection (continued). "The concentration of CRP in serum increases in microbial infections including Streptococcus pneumoniae infection." (PMID 33552084, 2020). "In mouse models of pneumococcal infection, transgenic or passively administered human CRP has been shown to be protective against lethal infection with S. pneumoniae." (PMID 31114584, 2019). "One host defense function of C-reactive protein (CRP) is to protect against Streptococcus pneumoniae infection as shown by experiments employing murine models of pneumococcal infection." (PMID 30863393, 2019). "Systemic pneumococcal infection raises the level of CRP in serum by up to several hundred-fold in humans as a part of the acute phase response." (PMID 30863393, 2019). "Recently, a CRP mutant capable of binding to immobilized factor H was evaluated for its ability to protect against late stage pneumococcal infection." (PMID 30863393, 2019). "More recently, the relative contributions of complement and FcγR were investigated in CRP-mediated protection from pneumococcal infection." (PMID 30483265, 2018). "In contrast to the results in pneumococcal infection, CRP protection in a mouse model of endotoxin shock was completely dependent on FcγR." (PMID 30483265, 2018). "Autologous mouse CRP is evidently essential for innate resistance to pneumococcal infection before antibodies are produced, probably by clumping the bacteria, limiting their spread and promoting their phagocytosis and destruction by neutrophils." (PMID 30459761, 2018). "Meanwhile, the protective function of mouse CRP against pneumococcal infection is the only function of any CRP to be firmly established so far in the same species." (PMID 30459761, 2018). "C-reactive protein (CRP) was discovered in 1930 during a study of patients with Streptococcus pneumonia infection." (PMID 26346216, 2015). "Autologous mouse CRP is evidently essential for innate resistance to pneumococcal infection before antibodies are produced." (PMID 24673624, 2014). "A member of the pentraxin protein family, CRP was first identified in the plasma of patients with Streptococcus pneumoniae infection." (PMID 24192039, 2013). "CRP levels rise dramatically during pneumococcal infection highlighting the importance of this acute phase protein as a sentinel molecule against this pathogen." (PMID 22957048, 2012). "CRP is an acute-phase protein, and in 1930, Tillett and Francis identified proteins responsive to the systemic C-polysaccharide response of Streptococcus pneumoniae in patients with acute pneumococcal infection, and it was later named CRP." (PMID 40313464, 2025). "Serum and salivary CRP levels were further compared in eight cases identified as Streptococcus pneumoniae infection by urine antigen, seven cases identified as influenza A virus by virus isolation, and 55 cases positive for serum Mycoplasma pneumoniae IgM with no other specific pathogen." (PMID 37189569, 2023). "The protective role of CRP against pneumococcal infection was proven." (PMID 37564652, 2023). "The availability of H38R CRP provided us with the needed tool to test the hypothesis that complement activation by PCh-complexed CRP is critical for CRP to protect mice against pneumococcal infection." (PMID 32903624, 2020). "Decades ago, it was hypothesized that complement activation by CRP complexed with PCh was responsible for CRP-mediated protection of mice against pneumococcal infection." (PMID 32903624, 2020). "Human CRP has been shown to protect mice against lethal pneumococcal infection." (PMID 32903624, 2020). "If this hypothesis is correct, then our findings provide a new strategy to treat pneumococcal infection by injecting exogenously prepared pre-modified CRP, such as E-CRP-1 and E-CRP-2." (PMID 33117400, 2020). "In this study, we tested a decades-old hypothesis that the complement-activating property of phosphocholine-complexed CRP contributes to protection of mice against pneumococcal infection." (PMID 32903624, 2020).
pneumococcal infection (continued). "Since complement-deficient mice do not show CRP-mediated protection to pneumococcal infection, it is possible that CRP-complexes are able to activate murine complement system via a pathway other than the classical pathway." (PMID 30863393, 2019). "Indeed, all patients with active pneumococcal infections have greatly increased plasma CRP concentrations and abundant circulating human CRP so CRP evidently does not control established pneumococcal sepsis." (PMID 30459761, 2018). "WBC levels may alter faster, especially during pneumococcal infection, whereas CRP peaks in approximately 48 hours after onset of fever." (PMID 26034987, 2015). "Thus, the PCh-binding function of CRP is defensive for the host because it leads to protection against pneumococcal infection and removal of necrotic tissue." (PMID 24948846, 2014). "Indeed, all patients with active pneumococcal infections have greatly increased plasma CRP concentrations and abundant circulating human CRP so it evidently does not control established pneumococcal sepsis." (PMID 24673624, 2014). "Additionally, levels of CRP were also much higher in patients with pneumococcal infection." (PMID 21801627, 2011). "The higher expression of the SAP gene in the absence of the CRP gene supports our interpretation that SAP plays a role in protecting against pneumococcal infection." (PMID 40740789, 2025). "C-reactive protein (CRP) is a homopentameric acute-phase inflammatory protein that was first discovered in serum in 1930 by Tillet and Francis while researching the serum of patients in the acute stage of pneumococcal infection." (PMID 38672162, 2024). "Mutant CRP did not bind to PCh and was used as a tool to investigate the importance of the PCh-binding site in CRP-mediated protection of mice against pneumococcal infection." (PMID 32849641, 2020). "H38R CRP incapable of activating murine complement failed to protect mice against lethal pneumococcal infection." (PMID 32903624, 2020). "Previously, we reported that CRP triple mutant, which does not bind to PCh, protected mice against infection and we interepreted the data to suggest that CRP protects mice against pneumococcal infection without binding to pneumococci." (PMID 33117400, 2020). "Employing a murine model of pneumococcal infection, we found that passively administered H38R CRP failed to protect mice against infection." (PMID 32903624, 2020). "Although a functioning complement system is required for full CRP-mediated protection, the exact mechanism of action of CRP in protecting mice against pneumococcal infection is not known." (PMID 32903624, 2020). "While native CRP is protective only against early stage infection, non-native pentameric CRP is protective against both early stage and late stage infections in murine models of pneumococcal infection." (PMID 30863393, 2019). "It is not known whether structurally altered CRP mimicking the ligand-binding properties of E-CRP-1 or E-CRP-2 is formed at sites of inflammation in vivo during pneumococcal infection." (PMID 40740789, 2025). "Interestingly, CRP is protective against pneumococcal infection only when injected 6 h before to 2 h after administering pneumococci into mice, that is, CRP is protective against early-stage infection but not against late-stage infection." (PMID 33117400, 2020). "The reason why CRP is not protective against late-stage pneumococcal infection is not known." (PMID 33117400, 2020). "The recruitment of factor H by pneumococci might be the reason why CRP does not protect mice from pneumococcal infections during late stage infection." (PMID 30863393, 2019). "However, employing animal models of pneumococcal infection it has been shown that the PCh-binding property of human CRP is not the only relevant ligand recognition function of human CRP." (PMID 31114584, 2019). "Accordingly, non-native CRP has also been found to be protective against pneumococcal infection." (PMID 31379851, 2019).
pneumococcal infection (continued). "Interestingly, administration of human CRP to mice protects against pneumococcal infections, but not if CRP is administered after exposure to the bacteria, suggesting an early prophylactic function may be associated with CRP levels." (PMID 28003312, 2017). "In this mouse model of pneumococcal infection, it has been reported previously that WT CRP does not increase the MST if mice received WT CRP 12 h after receiving pneumococci." (PMID 33552084, 2020).